MANEAL (mannosidase endo-alpha like)
Synonyms: FLJ31434
Tractability: Antibody: UniProt predicts a signal peptide or a membrane-spanning region. PROTAC: ubiquitination databases record sites on it; its protein half-life has been measured.
Gene: Protein-coding gene on chromosome 1 (37,793,847 to 37,804,557, forward strand). Ensembl gene ENSG00000185090.
Subcellular location: Golgi apparatus membrane
Subcellular location (Human Protein Atlas): Golgi apparatus
Gene Ontology:
Molecular function: alpha-mannosidase activity; hydrolase activity, acting on glycosyl bonds
Cellular component: Golgi membrane
Genetic constraint (gnomAD): Loss-of-function variants: 26 observed, 33.99 expected, observed/expected ratio (o/e) 0.76, 90% interval 0.56 to 1.06. The upper end of that interval is the gene's LOEUF score, 1.06, which puts it in group 4 of 6, group 1 being the genes least tolerant of losing a copy. Missense variants: 576 observed, 592.03 expected, observed/expected ratio (o/e) 0.97, 90% interval 0.91 to 1.04. Synonymous variants: 286 observed, 259.31 expected, observed/expected ratio (o/e) 1.1, 90% interval 1 to 1.22.
Homologues: Orthologues: chimpanzee MANEAL (99% identical), pig MANEAL (98% identical), mouse Maneal (95% identical), rat Maneal (95% identical), dog MANEAL (94% identical), macaque MANEAL (87% identical), tropical clawed frog maneal (72% identical), zebrafish maneal (67% identical), guinea pig MANEAL (57% identical), rabbit MANEAL (57% identical), Drosophila melanogaster CG14015 (26% identical). Paralogues in human: MANEA (57% identical).
Diseases named in the same sentence as MANEAL in open-access papers:
MANEAL is named in the same sentence as 2 diseases in open-access papers, as found by Europe PMC text mining. Sharing a sentence is not in itself a finding about the gene and the disease. The quoted sentences say what the papers report.
cancer (1 paper, 2020). A tumor composed of atypical neoplastic, often pleomorphic cells that invade other tissues. "(iii) More cancer-specific genes, including mannosidase, endo-alpha-like (MANEAL) that plays a role in the N-glycan maturation, are overexpressed only in cancer cell lines." (PMID 32365991, 2020).
tumor (1 paper, 2011). "A recent genomic methylation analysis of 12 ER+ and 12 ER− tumors identified 5 loci that are consistently hypermethylated in one or the other tumor type (MANEAL, PER1, NAV1, FAM124B, and ST6GALNAC1)." (PMID 21364760, 2011).